LY6H (lymphocyte antigen 6 family member H)
Diseases named in the same sentence as LY6H in open-access papers:
LY6H is named in the same sentence as 39 diseases in open-access papers, as found by Europe PMC text mining. Sharing a sentence is not in itself a finding about the gene and the disease. The quoted sentences say what the papers report.
ovarian carcinoma (4 papers, 2016 to 2024). A malignant neoplasm originating from the surface ovarian epithelium. "The lymphocyte antigen 6 family member LY6H has elevated expression in ovarian cancer, colorectal cancer, gastric cancer, breast cancer, and many other cancers, and it is related to poor prognosis in cancer patients." (PMID 33747079, 2021). "The LY6H module is altered in 24% of ovarian cancer subtype 1 cases and includes three altered genes, namely, DVL3, LY6H, and PPP1R16A." (PMID 26735889, 2016). "Ly6H mRNA expression was significantly increased in ovarian cancer (n=291) than normal tissues (n=19) in Bonome Lu and Hendrix studies." (PMID 26862846, 2016).
clear cell carcinoma of kidney (3 papers, 2016 to 2024). "Ly6H mRNA expression was significantly increased in clear cell carcinoma of kidney (n=256) than other types (n=59) in TCGA and Bittner(Unpublished, GSE2109) studies." (PMID 26862846, 2016).
Alzheimer disease (2 papers, 2012 to 2025). A progressive, neurodegenerative disease characterized by loss of function and death of nerve cells in several areas of the brain leading to loss of cognitive function such as memory and language. "This delicate balance is disrupted during Alzheimer’s disease due to Aβ-driven reduction in Ly6h." (PMID 40691194, 2025). "Notably, an increase in Ly6h in human cerebrospinal fluid correlates with elevated Alzheimer’s disease severity." (PMID 40691194, 2025).
breast carcinoma (2 papers, 2016 to 2021). "Ly6H mRNA expression was significantly increased in breast cancer (n=2567) than normal tissue (n=209) in TCGA (unpublished, NCI), Curtis study and Gluck studies." (PMID 26862846, 2016). "Increased Ly6H mRNA expression was significantly correlated with more aggressive phenotype of breast cancer - grade 2 (n=40) than grade 1 (n=40), gastric cancer - stage 3 (n=14) than stage 1 (n=4) in Curtis, and Cho studies." (PMID 26862846, 2016). "Ly6H mRNA expression was significantly higher in estrogen receptor (ER) positive breast cancer (n=562) than ER negative breast cancer (n=244) in Bittner (Unpublished, GSE2109), Wang, Stickeler and TCGA (Unpublished, NCI) studies." (PMID 26862846, 2016). "Ly6H mRNA expression was significantly higher in progesterone receptor (PgR) positive breast cancer (n=215) than PgR negative breast cancer (n=149) in Stickeler and TCGA (Unpublished, NCI) and Chang studies." (PMID 26862846, 2016).
colorectal cancer (2 papers, 2016 to 2021). A primary or metastatic malignant neoplasm that affects the colon or rectum. "Ly6H mRNA expression was significantly increased in colorectal cancer with KRAS mutation (n=27) than KRAS wildtype tumors (n=43) in Khambata-Ford study." (PMID 26862846, 2016). "High Ly6H mRNA expression in colorectal cancer was significantly correlated with poor five-year relapse free survival (low Ly6H, n=70; high Ly6E, n=70; HR=7.6, p=0.0326, n= number of patient, HR=hazard ratio) shown by PROGgeneV2." (PMID 26862846, 2016). "High Ly6H mRNA expression in colorectal cancer was significantly correlated with decreased five-year recurrence survival (recurrence, n=56 vs recurrence free, n=30) in Jorissen study." (PMID 26862846, 2016).
endometrial cancer (2 papers, 2021 to 2024). Primary or metastatic malignant neoplasm involving the endometrium (mucous membrane that lines the endometrial cavity). "Among them, CD3EAP and LY6H are prognostic risk genes for patients with endometrial cancer (HR > 1), while DMC1 and TLE2 are prognostic protective genes (HR < 1)." (PMID 33747079, 2021). "The results of Kaplan–Meier prognostic analysis showed that high expression of the risk-associated genes (B3GAT2, CD3EAP, FRMPD3, LINC01224, LINC02068, LY6H, and NR6A1) is related to poor prognosis in endometrial cancer patients (P < 0.05)." (PMID 33747079, 2021). "In contrast, LY6H expression is lower in cervical squamous cell carcinoma and endometrial adenocarcinoma (CESC), colon cancer (COAD), esophageal cancer (ESCA), rectal adenocarcinoma (READ), gastric adenocarcinoma (STAD), and endometrial cancer (UCEC) than in normal tissues." (PMID 39308669, 2024).
esophageal cancer (2 papers, 2016 to 2024). A primary or metastatic malignant neoplasm involving the esophagus. "Ly6H mRNA expression was significantly increased in esophageal cancer (n=104) than normal tissue (n=42) in Hao and Kim studies." (PMID 26862846, 2016).
gastric cancer (2 papers, 2016 to 2021). A primary or metastatic malignant neoplasm involving the stomach. "The survival data for colorectal, ovarian and gastric cancer showed that all four studied genes Ly6D, Ly6E, Ly6H, Ly6K are poor prognosis markers for multiple cancer types." (PMID 26862846, 2016). "High Ly6H mRNA expression in gastric cancer was significantly correlated with poor five-year first progression free survival (low Ly6H, n=336; high Ly6E, n=499; HR=1.5, p=6.9E-05) and five-year overall survival (low Ly6H, n=377; high Ly6E, n=499; HR=1.56, p=6E-07) shown by KM plotter." (PMID 26862846, 2016).
lung carcinoma (2 papers, 2016 to 2022). "The LY6 family, consisting of Ly6D, Ly6E, Ly6K and Ly6H, is also associated with poor survival in several cancer types, including lung cancer." (PMID 35574342, 2022). "Ly6H mRNA expression was significantly increased in lung cancer (n=47) than normal tissues (n=47) in Bhattacharjee and Su studies." (PMID 26862846, 2016).
prostate carcinoma (2 papers, 2016 to 2024). A carcinoma that arises from epithelial cells of the prostate gland. "This analysis showed that four different members Ly6D, Ly6E, Ly6H or Ly6K have increased gene expressed in bladder, brain and CNS, breast, colorectal, cervical, ovarian, lung, head and neck, pancreatic and prostate cancer than their normal counter part tissues." (PMID 26862846, 2016).
attention deficit-hyperactivity disorder (1 paper, 2015). A disorder characterized by a marked pattern of inattention and/or hyperactivity-impulsivity that is inconsistent with developmental level and clearly interferes with functioning in at least two settings (e.g. at home and at school). "Ly6h, a GPI-anchored protein, is a member of the Ly6 complex—a protein family involved in immune regulation—encoded by ≥ 20 genes many of which cluster in human chromosome 8q24.3, a hot spot of deletion/duplication events linked to ASD and attention deficit hyperactivity disorder." (PMID 25849048, 2015).
cervix cancer (1 paper, 2016). "Ly6H mRNA expression was significantly increased in cancerous tissue of cervix (n=8) than precursors cervix cancer (n=23) in Zhai study." (PMID 26862846, 2016).
CNS cancer (1 paper, 2016). "Ly6H mRNA expression was significantly higher in Myc amplified brain and CNS cancer (n= 50) than cancer without Myc amplification (n= 102) in Wang and Robinson studies." (PMID 26862846, 2016).
diffuse large B-cell lymphoma (1 paper, 2024). "Among them, Diffuse Large B-Cell Lymphoma and Ovarian Serous Cystadenocarcinoma have the highest incidence, suggesting that attention should be paid to the relationship between LY6H gene mutation and blood system and female reproductive system." (PMID 39308669, 2024).
head and neck cancer (1 paper, 2016). A primary or metastatic malignant neoplasm affecting the head and neck. "Ly6H mRNA expression was increased significantly in head and neck cancer (n=20) than normal tissue (n=9) in Schlingemann and Frierson studies." (PMID 26862846, 2016).
hepatocellular carcinoma (1 paper, 2024). A malignant tumor that arises from hepatocytes. "The results revealed that LY6H exhibited high expression levels in most cancers which were further validated through Reverse Transcription-Polymerase Chain Reaction (RT-PCR) and Immunohistochemistry (IHC) analysis using Hepatocellular carcinoma (HCC) samples." (PMID 39308669, 2024).
kidney cancer (1 paper, 2016). Primary or metastatic malignant neoplasm involving the kidney. "Ly6H mRNA expression was significantly increased in Kidney cancer (n=22) than normal tissue (n=8) in Yusenko and Cutcliffe studies." (PMID 26862846, 2016).
lobular breast cancer (1 paper, 2016). "Ly6H mRNA expression was significantly higher in lobular breast cancer (n=22) than ductal breast cancer (n=188) in Radvanyi and Desmedt studies." (PMID 26862846, 2016).
mastitis (1 paper, 2019). Inflammation of breast tissue during lactation or postpartum due to an obstructed duct or infection. "The putative role of these two genes (LY6H and LY6K) in immune response has been reported in several previous investigations and LY6K gene was reported to be a significant candidate gene for mastitis susceptibility in US and Chinese Holstein cattle." (PMID 31311492, 2019).
pancreatic cancers (1 paper, 2016). "The mRNA expression data across multiple studies shows that ovarian, colorectal, gastric, breast, lung, brain and CNS, cervical, esophageal, head and neck and pancreatic cancers express significant high levels of Ly6D, Ly6E, Ly6H, Ly6K." (PMID 26862846, 2016).
retinoblastoma (1 paper, 2024). A malignant tumor that originates in the nuclear layer of the retina. "Conversely in retinoblastoma (RB), we found that LY6H was positively correlated with angiogenic processes along with differentiation programs and inflammation-related pathways; whereas it exhibited an inverse relationship with DNA repair efficiency as well as cell cycle progression." (PMID 39308669, 2024).
uveal melanoma (1 paper, 2024). A melanoma derived from melanocytes of the uveal tract. "In uveal melanoma (UM), we observed a negative association between LY6H expression levels and DNA repair capacity, cellular quiescence status, DNA damage response pathways as well as differentiation potential, apoptosis susceptibility and inflammatory signaling cascades." (PMID 39308669, 2024).
cancer (9 papers, 2016 to 2025). A tumor composed of atypical neoplastic, often pleomorphic cells that invade other tissues. "The correlation heat maps we have generated demonstrate a significant association between LY6H expression and immune cell infiltration levels across the majority of cancer types." (PMID 39308669, 2024). "Of particular interest, the cg15721488 methylation site linked to LY6H expression exhibits hypermethylation in nearly all cancer types, highlighting its significance as a noteworthy methylated site." (PMID 39308669, 2024). "The AUC of the ROC curve further validated the exceptional diagnostic performance of LY6H across multiple cancer types." (PMID 39308669, 2024). "The present study employed a comprehensive bioinformatics analysis to elucidate the association between LY6H expression and the diagnosis, prognosis, as well as immune infiltration in various cancer types." (PMID 39308669, 2024). "In our study, we investigated the role of LY6H in TCGA human pan-cancer, encompassing diagnostic, clinical, and immunological features." (PMID 39308669, 2024). "Our methylation heat map reveals a predominant decrease in methylation levels at most DNA methylation sites associated with LY6H across various cancers." (PMID 39308669, 2024). "In our analysis of 20 cancer types, we found that hypomethylation of the LY6H promoter was associated with higher LY6H expression, suggesting a potential role in tumor progression." (PMID 39308669, 2024). "GAP43 and BASP1 have previously showed significant associations with tau concentration, together with for example the cancer-associated protein LY6H, and PEBP1 which is believed to have implications for AD." (PMID 33653397, 2021). "The correlation analysis of LY6H expression and immunomodulatory genes revealed a significant association between LY6H expression and immunomodulatory genes across various cancer types, including pivotal immune genes such as IL2RA (also known as CD25), IL-2, and CTLA423." (PMID 39308669, 2024). "The association between LY6H expression level and prognosis was investigated by performing survival association analysis for each type of cancer, including overall survival (OS), disease-free interval (DFI), and disease-specific survival (DSS), using Kaplan-Meier survival curves." (PMID 39308669, 2024). "Furthermore, the expression of LY6H was significantly associated with DNA methylation patterns in 21 cancers." (PMID 39308669, 2024). "By investigating the association between LY6H gene expression and stromalscore, immunescore, and estimatescore, we observed a significant positive correlation between LY6H expression and these three scores in the majority of cancer types." (PMID 39308669, 2024). "In addition, the upregulation of LY6H is associated with poor outcomes in terms of the patient survival rate, which makes it a novel biomarker of poor cancer prognosis and a therapeutic target for multiple cancers." (PMID 36364024, 2022). "The collective findings provide further evidence of the up-regulation of LY6H expression across various cancer types, thereby indicating the promising potential of LY6H in cancer diagnosis." (PMID 39308669, 2024). "Through the analysis of LY6H expression and tumor stemness, we have identified significant correlations between 16 types of cancer and tumor stemness." (PMID 39308669, 2024). "We utilized the cBioPortal database to conduct an analysis on the genetic alterations of LY6H across various cancer types." (PMID 39308669, 2024). "In recent years, the LY6H gene has garnered increasing attention due to its multifaceted involvement in cancer development, stem cell maintenance, immune regulation, and association with more aggressive and refractory cancers." (PMID 39308669, 2024). "By excluding insufficient normal samples, duplicate samples, and samples with 0 mRNA expression, we observed significant differences in the expression levels of LY6H between tumor and normal tissues across 16 types of cancer." (PMID 39308669, 2024).
cancer (continued). "We utilized the TISIDB database to conduct an analysis on the expression patterns of molecular and immune subtypes of LY6H across various cancer types." (PMID 39308669, 2024). "Based on the TCGA data we downloaded, we compared LY6H expression levels in 33 cancer patients with matched normal samples, excluding those with no normal tissue data or with very few normal samples." (PMID 39308669, 2024). "To investigate the underlying mechanisms driving tumor progression, we utilized the UALCAN online tool to assess the methylation levels of LY6H promoter in distinct cohorts of cancer patients and healthy individuals." (PMID 39308669, 2024). "Our findings revealed that LY6H exhibited expression in twelve distinct molecular subtypes of cancer." (PMID 39308669, 2024). "We utilized the ESTIMATE algorithm to compute the stromalscore, immunescore, and estimatescore of LY6H expression across 33 cancer types, subsequently generating a correlation scatter plot." (PMID 39308669, 2024). "Our findings aim to identify potential broad-spectrum biomarkers for cancer diagnosis by highlighting the significant up-regulation of LY6H in various cancer types and its potential utility in early detection." (PMID 39308669, 2024). "To examine the status of Ly6H in human cancer, we used Oncomine or G-DOC to analyze gene expression omnibus (GEO) datasets." (PMID 26862846, 2016). "Besides LY6A/LY6S, other LY6 family members have been suggested as close homologues of the murine Ly6a gene, such as LY6D, LY6E, LY6H and LY6K, which were implicated as biomarkers for poor cancer prognosis and are frequently amplified in human cancer." (PMID 39642167, 2025). "Additionally, it was found that LY6H played a pivotal role in regulating immune-infiltrating cells across multiple cancers whereas the correlation between LY6H expression and immune-related genes varied depending on their specific types." (PMID 39308669, 2024). "We detected significant differences in LY6H expression from normal tissues in 16 cancers." (PMID 39308669, 2024). "Increased expression of Ly6D, Ly6E, Ly6H or Ly6K was observed in sub-set of cancer type." (PMID 26862846, 2016). "By examining the correlation between LY6H expression and tumor mutational burden(TMB), microsatellite instability (MSI), and mutation-associated thermodynamic stability(MATH) genes, we observed a significant association between LY6H expression and TMB across multiple cancer types." (PMID 39308669, 2024). "LY6/uPAR superfamily members, such as LY6E, LY6H, LY6K, and PSCA, are overexpressed in various cancers and contribute to tumor growth, invasion, and metastasis." (PMID 39727968, 2024).
tumor (5 papers, 2016 to 2025). "Additionally, this paper delved into methylation levels of LY6H along with drug sensitivity analysis, mutation analysis and chemical analysis to provide insights into elucidating the mechanism underlying tumor development." (PMID 39308669, 2024). "Simultaneously, we examined the correlation between LY6H and tumor stemness, methylation patterns, drug sensitivity, gene alterations as well as single cell functions." (PMID 39308669, 2024). "LY6H exhibited a strong correlation with immunotherapy-related characteristics such as immune cells, immunomodulatory genes, immune checkpoints, tumor stemness, and TMB, thereby highlighting its potential as an immunotherapy predictor." (PMID 39308669, 2024). "The correlation analysis between tumor stemness and LY6H expression revealed significant correlations in 16 tumors." (PMID 39308669, 2024). "By utilizing patient data from multiple databases, we conducted analyses on immune infiltration, single-cell functionality, methylation patterns, drug sensitivity profiles, gene enrichment pathways; furthermore, we explored genetic alterations of LY6H and its correlation with tumor stemness." (PMID 39308669, 2024). "In contrast, in paired tumor samples, LY6H expression was significantly reduced in STAD." (PMID 39308669, 2024). "We conducted an investigation into the correlation between LY6H expression levels and prognosis, with a specific focus on survival association analysis of overall survival (OS), disease-specific survival (DSS), and progression-free interval (PFI) for each tumor type." (PMID 39308669, 2024). "Furthermore, LY6H exhibits interactions with both tumor cells and immune cells." (PMID 39308669, 2024). "Moreover, LY6H displayed early diagnostic potential in 12 tumors while also showing positive or negative correlations with prognosis across different tumor types." (PMID 39308669, 2024). "Therefore, LY6H could serve as an adjunctive biomarker for early tumor detection as well as a prognostic indicator for diverse malignancies." (PMID 39308669, 2024). "However, it is important to note that our study only validated the differential expression of LY6H in HCC, necessitating further investigation into the specific role of LY6H in each tumor type." (PMID 39308669, 2024). "We calculated the correlation between LY6H expression and TMB in each tumor, and observed a significant negative correlation in 5 tumors, such as KIRP (P=0.02), THYM (P=0.03), UCS (P=0.02), BLCA (P=0.03), ACC (P=0.04)." (PMID 39308669, 2024).
neurological disorders (2 papers, 2021 to 2024). "Thirteen OB proteins were differentially regulated in at least three neurological disorders, of which four of them (NCAM2, LY6H, COL6A3 and PRDX6) presented a homogeneous OB profile across diseases." (PMID 34768771, 2021).
LY6H also shares sentences with these, for which no sentence is quoted: bladder cancer (1 paper); bladder urothelial carcinoma (1); cervical squamous cell carcinoma (1); cholangiocarcinoma (1); colon cancer (1); endometrial adenocarcinoma (1); gastric adenocarcinoma (1); head and neck squamous cell carcinoma (1); lung squamous cell carcinoma (1); ovarian serous cystadenocarcinoma (1); pancreatic ductal adenocarcinoma (1); pheochromocytoma and paraganglioma (1); primary liver cancer (1); rectal adenocarcinoma (1).